P3H2 (prolyl 3-hydroxylase 2)
Description:
Prolyl 3-hydroxylase that catalyzes the post-translational formation of 3-hydroxyproline on collagens. Contributes to proline 3-hydroxylation of collagen COL4A1 and COL1A1 in tendons, the eye sclera and in the eye lens capsule (By similarity). Has high activity with the type IV collagen COL4A1, and lower activity with COL1A1. Catalyzes hydroxylation of the first Pro in Gly-Pro-Hyp sequences where Hyp is 4-hydroxyproline. Has no activity on substrates that lack 4-hydroxyproline in the third position.
Synonyms: LEPREL1; MLAT4; FLJ10718; MCVD
Tractability: Antibody: UniProt predicts a signal peptide or a membrane-spanning region. PROTAC: ubiquitination databases record sites on it.
Gene: Protein-coding gene on chromosome 3 (189,956,728 to 190,122,437, reverse strand). Ensembl gene ENSG00000090530.
Subcellular location: Endoplasmic reticulum; Sarcoplasmic reticulum; Golgi apparatus
Subcellular location (Human Protein Atlas): Golgi apparatus; Cytosol; Nucleoplasm; Vesicles
Pathways (Reactome):
Extracellular matrix organization: Collagen biosynthesis and modifying enzymes
Gene Ontology:
Molecular function: procollagen-proline 3-dioxygenase activity; iron ion binding; L-ascorbic acid binding; oxidoreductase activity, acting on paired donors, with incorporation or reduction of molecular oxygen
Biological process: collagen metabolic process; negative regulation of cell population proliferation; peptidyl-proline hydroxylation
Cellular component: endoplasmic reticulum; Golgi apparatus; basement membrane; endoplasmic reticulum lumen; sarcoplasmic reticulum
Genetic constraint (gnomAD): Loss-of-function variants: 55 observed, 55.15 expected, observed/expected ratio (o/e) 1, 90% interval 0.8 to 1.25. The upper end of that interval is the gene's LOEUF score, 1.25, which puts it in group 5 of 6, group 1 being the genes least tolerant of losing a copy. Missense variants: 849 observed, 729.91 expected, observed/expected ratio (o/e) 1.16, 90% interval 1.1 to 1.23. Synonymous variants: 324 observed, 279.7 expected, observed/expected ratio (o/e) 1.16, 90% interval 1.06 to 1.27.
Homologues: Orthologues: chimpanzee P3H2 (99% identical), macaque P3H2 (98% identical), rabbit P3H2 (93% identical), pig P3H2 (93% identical), dog P3H2 (92% identical), rat P3h2 (89% identical), mouse P3h2 (89% identical), guinea pig P3H2 (71% identical), tropical clawed frog p3h2 (62% identical), zebrafish p3h2 (54% identical). Paralogues in human: P3H1 (50% identical), P3H3 (41% identical).
Diseases named in the same sentence as P3H2 in open-access papers:
P3H2 is named in the same sentence as 28 diseases in open-access papers, as found by Europe PMC text mining. Sharing a sentence is not in itself a finding about the gene and the disease. The quoted sentences say what the papers report.
myopia (9 papers, 2017 to 2025). "Mutations in the P3H2 gene can result in high myopia, lens subluxation, cataract formation, and a predisposition to retinal detachment." (PMID 35499085, 2022). "Next, we analyzed patients with ocular abnormalities (e.g., myopia, cataract, lens luxation) related to P3H2 mutations for urinary abnormalities." (PMID 35499085, 2022). "P3H2 is a protein coding gene, and mutations in the gene are associated with severe non‐syndromic myopia with cataracts and vitreoretinal degeneration." (PMID 33934516, 2021). "In addition to the novel mutations found in five known myopia genes (ADAMTS18, CSMD1, P3H2, RPGR, and SLC39A5), we also identified pathogenic variants in seven ocular disease genes (ABCA4, CEP290, HSPG2, PCDH15, SAG, SEMA4A, and USH2A) as novel candidate genes." (PMID 30245926, 2018).
breast carcinoma (6 papers, 2009 to 2021). "The restriction of silencing in P3H2 to breast carcinomas, and its association with oestrogen-receptor-positive cases, suggests that P3H2 may be a breast-cancer-specific tumour suppressor." (PMID 19436308, 2009). "However, mRNA analysis implies that down-regulation of P3H2 is associated with less favourable prognosis in some breast cancer series and recurrence after tamoxifen." (PMID 19436308, 2009). "The specificity of down-regulation of P3H2 mRNA in breast cancer may reflect the association with oestrogen-receptor-positive primary breast cancers, an association also noted in breast carcinoma cell lines." (PMID 19436308, 2009). "Methylation inactivation of tumor suppressor genes such as P3H2 and PAMR1 were involved in the pathogenesis of breast cancer, but loss of these genes may be important for pathogenesis of GBM." (PMID 31137733, 2019). "In this respect, it will clearly be of interest to determine whether loss of expression of P3H2 and/or P3H3 affects the properties of the basement membrane in breast cancer cells and thereby influences cancer-associated phenotypes such as invasiveness and metastasis." (PMID 19436308, 2009). "Taken together, our results suggest that P3H2 and P3H3 are candidate tumour suppressors in breast cancer, raising the question of which function(s) are selected against during tumourigenesis." (PMID 19436308, 2009). "This study examined the epigenetic regulation of P3H1, P3H2 and P3H3 expression in breast cancer cell lines and in a panel of breast carcinomas." (PMID 19436308, 2009). "The prolyl 3-hydroxylases P3H2 and P3H3 are, therefore, novel candidate tumour suppressor genes in breast cancer." (PMID 19436308, 2009). "Using RT–PCR, we analysed the expression of the P3H1, P3H2 and P3H3 genes in breast carcinoma cell lines." (PMID 19436308, 2009). "Expression of P3H2 (Leprel1) and P3H3 (Leprel2) but not P3H1 (Leprecan) is down-regulated in breast cancer by aberrant CpG methylation in the 5′ regulatory sequences of each gene." (PMID 19436308, 2009).
focal segmental glomerulosclerosis (2 papers, 2022 to 2025). A renal disorder characterized by sclerotic lesions in the glomeruli. "Mice with podocyte‐specific knockout of P3H2 develop thin basement membrane nephropathy, which finally leads to focal segmental glomerulosclerosis confirming observations of patients harboring P3H2 mutations and suggesting a permanent activity of podocytes in GBM modification." (PMID 40698593, 2025).
glomerular disease (1 paper, 2022). "In summary, these data prove that P3h2 deletion affects the GBM as early as 6 weeks and that the mice developed a more severe phenotype at later stages of life, indicating progressive glomerular disease." (PMID 35499085, 2022).
microhematuria (1 paper, 2022). "Characterization of a P3h2ΔPod mouse line revealed that the absence of P3H2 protein in podocytes induced a thin basement membrane nephropathy (TBMN) phenotype with a thinner GBM than that in WT mice and the development of microhematuria and microalbuminuria over time." (PMID 35499085, 2022).
Nephropathy (1 paper, 2022). A nonspecific term referring to disease or damage of the kidneys. "Finally, we should mention a most recent mouse model created to recapitulate thin basement membrane nephropathy caused by null mutations in the prolyl 3-hydroxylase 2 (P3h2) gene, which hydroxylates 3′-prolines of the collagen IV alpha chains (Gly-3Hyp-4Hyp-Gly)." (PMID 36292778, 2022).
cancer (11 papers, 2009 to 2025). A tumor composed of atypical neoplastic, often pleomorphic cells that invade other tissues. "Furthermore, the putative novel miRNA EGCG-MDAMB231-5 targets MBP (Myelin Basic Protein), HIC1 (hypermethylated in cancer 1), and P3H2 (Prolyl 3-Hydroxylase 2), SLC6A2 (Solute Carrier Family 6 Member 2) genes." (PMID 36276982, 2022). "P3H1 was expressed in all 13 carcinoma cell lines in our panel, but there was no detectable expression of P3H2 mRNA in MDA MB 361, MDA MB 453, MCF7 and T47D cell lines, with only low levels of expression in BT474 and SKBR3." (PMID 19436308, 2009).
tumor (11 papers, 2009 to 2026). "The analysis of drug sensitivity indicated that increased expression of members from the P3H family, particularly P3H3 and P3H2, is strongly associated with heightened resistance to specific therapeutic drugs used for treating tumors, suggesting their role in mechanisms leading to tumor resistance." (PMID 38706607, 2024). "P3H2 overexpression remodeled the tumor microenvironment (TME) by modifying its main substrate, Collagen IV, resulting in the induction of increased vessels density." (PMID 41752135, 2026). "We speculated that a low expression of P3H2 could affect the properties of the basement membrane, which could facilitate the degradation by the enzyme secreted by tumor cells." (PMID 24319452, 2013). "In general, the expression of P3H2, COL10A1, and C5 in tumor tissues was significantly increased than that in normal tissues, and the expression of UHRF1, considered as a tumor suppressor gene, was higher in normal tissues than in tumor tissues." (PMID 33934516, 2021). "Notably, individuals with elevated expression of P3H2, P3H3, and CRTAP exhibited higher resistance to multiple anti-tumor drugs." (PMID 38706607, 2024).
genetic diseases (1 paper, 2018). "Mutations in CRTAP, P3H1 and P3H2 cause human genetic diseases." (PMID 30417103, 2018).
P3H2 also shares sentences with these, for which no sentence is quoted: bladder cancer (2 papers); hepatocellular carcinoma (2); lung carcinoma (2); vitreoretinal degeneration (2); cataract (1); colorectal cancer (1); embryonal carcinoma (1); exudative vitreoretinopathy (1); Familial exudative vitreoretinopathy (1); gastric cancer (1); gastrointestinal disease (1); glioma (1); malignant melanoma (1); membrane nephropathy (1); prostate carcinoma (1); renal adenocarcinomas (1); retinal detachment (1); thin basement membrane nephropathy (1); thyroid cancer (1).